TNF (tumor necrosis factor)
Diseases named in the same sentence as TNF in open-access papers (continued):
Sharing a sentence is not in itself a finding about the gene and the disease.
hepatocellular carcinoma (continued). "Especially in the liver, TNF-alpha is involved in numerous biological outcomes such as hepatocyte apoptosis and necroptosis, liver inflammation, and hepatocellular carcinoma." (PMID 41141269, 2025). "Sequestration of NF-κB in the cytoplasm protects the activation of genes dependent on NF-κB, sensitizes hepatocytes against apoptotic stimuli such as TNFα, and sensitizes human hepatoma cells to daunorubicin and/or ionizing radiation." (PMID 38254878, 2024). "ETV4 is a transcription activator of TNF‐α, promoting hepatic inflammation in hepatocellular carcinoma." (PMID 39228892, 2024). "A preclinical study has demonstrated that emodin can induce apoptosis in hepatocellular carcinoma cells and increase cancer cell death by triggering the expression of TNF-α." (PMID 39056768, 2024). "Berberine and diosmin combination forms nano‐micelles, which showed anticancer activity in hepatocellular carcinoma mice by downregulating angiogenesis and TNF‐α, COX‐2, NF‐κB, and TNF‐α, and through the initiation of apoptosis." (PMID 39554345, 2024). "Transforming growth factor α (TNF-α) is also believed to promote the development of hepatocellular carcinoma." (PMID 39408564, 2024). "In SMMC‐7721 hepatocellular carcinoma cells and nude mice subcutaneous tumor models, TNF‐α produced by TAMs promotes EMT and CSC via Wnt/β‐catenin pathway." (PMID 38098217, 2023). "Several studies have observed that individuals with the hepatitis C virus and hepatocellular carcinoma have higher levels of TNF-α, supporting the relevance of this pro-inflammatory cytokine in hepatocarcinogenesis and HCV infection." (PMID 36674897, 2023). "Recent evidence suggests that cathepsin C interacts with TNF-α/p38 mitogen activated protein kinase (MAPK) signaling pathways to promote hepatocellular carcinoma proliferation and metastasis." (PMID 37035802, 2023). "The previous findings in regard that SC79 would significantly alleviate TNF-α-induced apoptosis in both the cultured human hepatocellular carcinoma cells and the primary mouse hepatocytes through activation of AKT." (PMID 36829992, 2023). "MiR‐98 mimics notably elevate the levels of IL‐1β and TNF‐α in TAM under hepatocellular carcinoma conditions, but significantly lower IL‐10 and TGF‐β, meaning that M2 turns into M1, thus repressing EMT, invasion, and migration of SMMC7721 and HepG2 cells." (PMID 38098217, 2023). "For instance, in hepatocellular carcinoma, treatment of MSCs with IFNγ and TNFα leads to a high expression level of TGFβ which in turn induces EMT-related properties in tumor cells." (PMID 35251985, 2022). "As for the hepatitis B virus, its core protein has been shown to disrupt the interaction between MKK7 and RACK1, thereby enhancing tumor necrosis factor-α (TNF-α)-induced apoptosis in HepG2 human hepatoma cells." (PMID 35265209, 2022). "Core 4a and core 4f stably expressing Huh7.5 hepatoma cell lines, treated with TNFα and cycloheximide, showed similar death responses when compared to control cells." (PMID 36423130, 2022). "Intrahepatic Vγ9Vδ2 T-cells isolated from fresh human liver tissue exhibited minimal IFN-γ and TNF-α production in response to co-culture with HepG2 or HuH7 human hepatoma cell lines." (PMID 35296658, 2022). "In this study, we found that the combination of TNF-α and TPL accelerated apoptosis in human hepatocellular carcinoma cells and TNF-α-induced elevated as well as basal level of FLIPS protein were downregulated by TPL." (PMID 36308574, 2022). "We extracted PNG using different extraction methods and compared their MMP-9 inhibitory effects using tumor necrosis factor (TNF)-α-treated rat cardiomyocytes (H9c2) and human hepatoma cells (HepG-2) as the bioassays." (PMID 36432152, 2022).
hepatocellular carcinoma (continued). "TNF-α expression is related to SORA resistance in hepatocellular carcinoma cells and the regulation of autophagy levels." (PMID 36559076, 2022). "Its anti‐tumour properties have also been elucidated in a study on the human hepatoma cell line, HepG2, where it induced apoptosis by increasing the levels of IL‐1α and TNF‐α in those cells." (PMID 35838746, 2022). "Genes were mainly enriched in PI3K-Akt signaling pathway, IL-17 signaling pathway, TNF signaling pathway, apoptosis pathway, and hepatocellular carcinoma pathway." (PMID 36699068, 2022). "miR-224-5p has been primarily described as a hepatomiR, and its expression is elevated by the NFkB inflammatory pathway activated by TNF-alpha in Hepatocellular Carcinoma Cells." (PMID 35850658, 2022). "In palmitic acid (PA)-treated human hepatocellular carcinoma HepG2 cells, the downregulation of miR-375 expression significantly reduced IL-6, TNF-α, and leptin, and increased adiponectin levels." (PMID 36613525, 2022). "Here, used Hepa1-6 and Huh7 cells to establish the inflammatory hepatocellular carcinoma model promoted by TNF-α to explore the relationship between TMAO and the pathogenesis of inflammatory HCC promoted by TNF-α." (PMID 35676936, 2022). "In hepatocellular carcinoma, the lncRNA SPRY4-IT1 associates with HNRNPL to promote growth and metastasis through the tumor necrosis factor (TNF) pathway." (PMID 34543262, 2021). "In vitro, ADAM8 expression was upregulated in hepatoma, endothelial, and stellate cell lines by various mediators of steatohepatitis including fatty acid (linoleic-oleic acid), IL-1β, TNF-α, IFN-γ, and TGF-β." (PMID 33814981, 2021). "In mice, while only a small fraction of BM HSPCs expressed GM-CSF, IL-6, or TNF-α, approximately 40% of splenic LSK cells, both in tumor-free and orthotopic hepatoma-bearing mice, expressed TNF-α, suggesting niche-dependent functional heterogeneity." (PMID 33936078, 2021). "In this study, we confirmed that TNFα significantly augments the PD-L1-inductive effect of IFNγ in HepG2 cells, a human hepatocellular carcinoma cell line, and this effect was through activation of STAT1, JNK, and NFкB pathways." (PMID 34445462, 2021). "In our study, the signal pathways enriched for DEGs are mostly related to the small-molecule metabolic pathways and cancer-related signal pathways such as the mTOR signaling pathway, hepatocellular carcinoma, TNF signaling pathway, and mTOR signaling pathway." (PMID 34504838, 2021). "In human hepatoma cell line HepG2 cells, HBx induces lipid peroxidation through suppressing selenoprotein P, thereby increasing TNFα expression." (PMID 34615538, 2021). "GAR has previously shown to have reduced inflammatory markers like TNF-α and NF-κB in hepatic inflammation in the steatohepatitis-derived hepatocellular carcinoma of a mouse model (STAM) and LPS-induced inflammation in THP-1 cells in vitro." (PMID 33799680, 2021). "The KEGG results focused on the TNF signaling pathway, fluid shear stress, apoptosis, NF-kappa B signaling pathway, hepatocellular carcinoma, and other regulatory pathways; prompt NAMPT gene were associated with tumorigenesis." (PMID 33540574, 2021). "This study aimed to investigate the effects of tumor-related cytokines, interferon gamma (IFNγ), and tumor necrosis factor alpha (TNFα) on PD-L1 expression in human hepatocellular carcinoma cells, HepG2." (PMID 34445462, 2021). "Ectopic expression of HBSP in hepatoma cells restricts TNFα-mediated hepatic inflammation and subsequently reduces the immune infiltration in liver." (PMID 34526974, 2021). "In vitro experiments demonstrated that TNF-α induced SAA expression in mouse hepatoma Hepa1–6 cells, and these two signaling factors induced DNA damage in bone marrow mesenchymal stem cells (BMSCs) by increasing reactive oxygen species (ROS)." (PMID 34576128, 2021).
hepatocellular carcinoma (continued). "Nanocapsulated quercetin significantly reduced the incidence of hepatocellular carcinoma in rats and decreased the production of TNF-α and IL-6 in liver induced by diethyl nitrosamine." (PMID 33425996, 2020). "Inhibition of TNF-alpha expression can promote the recurrence and metastasis of hepatocellular carcinoma." (PMID 32075046, 2020). "It had been suggested that the progression and immune escape of hepatocellular carcinoma were closely related to the decrease of the NK cell number and function (TNF-α and IFN-γ) in the tumor microenvironment." (PMID 32075046, 2020). "Activated NK cells can enhance the sensitivity to hepatoma cells and specifically dissolve by releasing a variety of cytokines (TNF-α and IFN-γ), perforin, and high expression of FasL, CD16, and TRAIL." (PMID 32075046, 2020). "Research focusing on the relationship between five types of tumor necrosis factor-alpha (TNF-α) SNPs and the risk of hepatocellular carcinoma (HCC) were still controversial." (PMID 33228594, 2020). "A number of studies demonstrating FUZHENG Yiliu’s effects on hepatoma cells have been published showing an increase in CD3+, CD4+ and NK cells in peripheral blood with an increase in IL-2 and TNF-α, thus inhibiting hepatocellular cancer proliferation." (PMID 32372963, 2020). "The anti-inflammatory effect in the sciatic nerve chronic constriction injury (CCI)-induced neuropathic pain model and anticancer effect in the hepatocellular carcinoma (HCC) animal model are reported to be caused by RosA, which regulates the expression of TNF-α, COX-2, IL-1β, and p65." (PMID 32823673, 2020). "In vitro evidence suggests, for example, that propionate and cisplatin synergistically induce apoptosis of HepG2 hepatocellular carcinoma cells by increasing expression of TNF-α via reduction of histone deacetylases through GPR41 signaling." (PMID 32664466, 2020). "Previous studies showed that DHA inhibited cell proliferation and induced apoptosis in human hepatocellular carcinoma cells by upregulating TNF expression via JNK/NF-κB pathways." (PMID 33658929, 2020). "For example, in hepatoma cells, TNF-induced activation of MAT2B further promoted tumor growth via NF-κB pathway." (PMID 31686458, 2019). "DHA inhibited cell proliferation and induced apoptosis in human hepatocellular carcinoma cells by upregulating TNF expression via JNK/NF-κB pathways." (PMID 31534470, 2019). "Specifically, after treatment of NM combined with gemcitabine in gallbladder cancer, with paclitaxel in gastric cancer or with TNF-α in hepatocellular carcinoma, depression of NF-κB activation was stimulated." (PMID 31552177, 2019). "Previous observations have shown that hepatocellular carcinoma cell lines become more sensitive to taxol when it is combined with Tumor Necrosis Factor α (TNFα)." (PMID 31653043, 2019). "The lysosomal degradation product of ceramide, sphingosine, was required for TNFα/CHX-induced apoptosis in hepatoma cells via induction of lysosomal membrane permeabilization." (PMID 31637258, 2019). "It has been demonstrated that TNFα leads to the induction of lipogenic enzymes in an SREBP-1-dependent manner in ethanol-exposed hepatoma cell lines." (PMID 29735928, 2018). "For example, TNF-α can promote the expression of tenascin-C in hepatoma cells and promote metastasis of cancer cells." (PMID 30442110, 2018). "C3, which is included in three pathways leading to the activation of membrane-attack complexes on the target cell, is produced by rat hepatoma cells in response to inflammatory cytokines, such as IL-1 and tumor necrosis factor." (PMID 29513714, 2018). "More recently, TNF was shown as a mediator for the combinatorial effects of endoplasmic reticulum (ER) stress and hypernutrition in liver hyperplasia and hepatocellular carcinoma." (PMID 30345259, 2018).
hepatocellular carcinoma (continued). "To develop a mathematical model for TNFα-induced NFκB signal transduction, we generated time-resolved data of several pathway components of the canonical NFκB pathway in the human hepatocellular carcinoma cell line HepG2 and in PHHs." (PMID 29900006, 2018). "There is recent evidence that LRG1 is induced by IL-6 and synergistically up-regulated with either IL-1β or tumor necrosis factor-α in a pattern similar to that exhibited by type 1 acute-phase proteins in human hepatoma HepG2 cells." (PMID 29513714, 2018). "Evidence has shown that most hepatocellular carcinoma (HCC) cells are resistant to tumor necrosis factor (TNF)-related apoptosis-inducing ligand (TRAIL)-mediated apoptosis." (PMID 29444104, 2018). "For example, SelP expression is downregulated by TNFα stimulation of 3T3-L1 cells, by IL-6 in human hepatoma cells, and studies of the human SelP promoter have shown it is responsive to IL-1β, IFNγ and TNFα in HepG2 cells." (PMID 30571741, 2018). "TCR-transduced T cells were polyfunctional, secreting the cytokines interferon gamma, tumor necrosis factor alpha and interleukin-2, and effectively killed hepatoma cells replicating HBV." (PMID 28792537, 2017). "Genetic polymorphisms of TNF-α, VEGF, and UGT1A9 genes have been reported to be a link between HFSRs in patients with hepatocellular carcinoma treated with sorafenib." (PMID 28487491, 2017). "In human neurons, GLS1 expression was upregulated by IL-1β or TNF-α treatment, and in a rat hepatoma model IL-6 or TNF-α treatment indirectly upregulated c-MYC expression." (PMID 28399896, 2017). "TNF-α in the tumour microenvironment induces TNC expression in hepatocellular carcinoma (HCC) cells through the NF-κB pathway and then promotes HCC migration." (PMID 29088796, 2017). "On a cellular level, we demonstrate that IFNβ potently synergizes with the prototypic inflammatory cytokines IL-1β/TNFα for induction of iNOS in primary murine hepatocytes and murine Hepa56.1D as well as Hepa1-6 hepatoma cells." (PMID 28824623, 2017). "In this regard, we identified in murine Hepa1-6 hepatoma cells a potent synergism between pro-inflammatory interleukin-β/tumor necrosis factor-α and immunoregulatory IFNβ as detected by analysis of iNOS expression and nitrite release." (PMID 28824623, 2017). "Synergism between IL-1β/TNFα and IFNβ for iNOS expression was actually even more pronounced in alternate murine Hepa56.1D hepatoma cells." (PMID 28824623, 2017). "Our results showed that the long form of c-FLIP (c-FLIPL) is highly expressed in the human hepatoma cell line HepG2 independently of TNFα stimulation (second line)." (PMID 27518192, 2016). "NF-κB and AP-1 are required for basal MAT2A expression and the tumor necrosis factor-α (TNF-α)-induced transactivation of MAT2A in human hepatoma cells." (PMID 26418898, 2016). "Metastasis of hepatocellular carcinoma (HCC) can be facilitated by TNF-α, a prototypical inflammatory cytokine in the HCC microenvironment." (PMID 26909601, 2016). "Human hepatoma cells and primary murine hepatocytes were treated with TNF-α/LPS/IL-6/IL-10 and USP18, phosphorylated (p)-STAT1 and myxovirus (influenza virus) resistance 1 (Mx1) expression was determined." (PMID 27009955, 2016). "In vitro experiments also found mast cells can inhibit the expression of c-myc in hepatocellular carcinoma, and displayed antitumor effects via release of tumor necrosis factor (TNF), interleukin prime (IL) and other substances." (PMID 27835573, 2016). "In fact, induction of IL-36γ was detected in cultured murine primary hepatocytes or human Huh7 hepatocellular carcinoma cells exposed to inflammatory IL-1/TNFα/IFNγ." (PMID 25687687, 2015). "Here, we have performed a genome-wide search for endogenous SND1 binding sites by chromatin immunoprecipitation (ChIP)-chip assays on human hepatoma HepG2 cells in normal and TNFα-induced inflammatory conditions." (PMID 26323317, 2015).
hepatocellular carcinoma (continued). "The TNF-α-induced signal transduction pathway has been shown to be a possible target of gefitinib in suppressing the intrahepatic metastasis of hepatocellular carcinoma." (PMID 26160843, 2015). "This is consistent with higher proinflammatory cytokines (IL-1β, IL-6 and TNF) in hepatoma compared with healthy tissues." (PMID 27551463, 2015). "Ectopic expression of this miRNA enhances the chemosensitivity of hepatocellular carcinoma cells to TNF-α and doxorubicin." (PMID 25557171, 2015). "SBS decreases the tumor weight and increases serum interleukin 2 (IL-2), interferon-γ (IFN-γ) and tumor necrosis factor-α (TNF-α) in mice with xenografted hepatocellular cancers." (PMID 25897964, 2015). "A synergistic cytotoxicity was identified between pevonedistat and TNF-α in the rat hepatoma H-4-II-E cell line." (PMID 27551465, 2015). "For example, suppression of NF-κB by anti-TNF-α leads to an inhibition of disease progression in hepatocellular carcinoma." (PMID 24629025, 2014). "HepG2 cells (human hepatocellular carcinoma cell line) can be induced to release HMGB1 by treatment with LPS or TNF-α in a time- and dose-dependent fashion." (PMID 25187820, 2014). "Together, these data highlight a role for TNF-α in regulating hepatoma tight junction and CD81 dynamics, providing a mechanism for the increase in viral permissivity." (PMID 24259385, 2014). "The ability of TNF-α to promote the permissivity of polarized hepatoma cells was not limited to HCV but was seen with lentiviral pseudotypes expressing Lassa, measles, and VSV-G glycoproteins." (PMID 24259385, 2014). "TNF-α has also been implicated as a disease promoter in hepatocellular carcinoma (HCC), from chronic inflammation to tumor progression including invasion, metastasis, and angiogenesis in established HCC tumors." (PMID 24672527, 2014). "We found that TNF-alpha was heightened in all three examined hepatoma cell lines indicating a proinflammatory potential of pK1-5." (PMID 24895598, 2014). "The transcription of cytochrome P450 genes, including CYP3A11, moreover is reportedly suppressed by immune responses such as TNF-α in primary hepatocytes and hepatoma cells." (PMID 24410935, 2014). "Human hepatoma HuH-7 cells exposed to rHDLs showed suppressed TNFα-induced NF-κB activation, correlating with decreased NF-κB target gene expression." (PMID 24347528, 2014). "There has also been a case report of hepatocellular carcinoma in a patient treated with a TNF-α antagonist in combination with azathioprine." (PMID 24707412, 2014). "Although, it is induced by IL-6, IL-1-β and TNF-α in hepatoma cells, and overexpressed in the liver of mice challenged by lipopolysaccharide rendering it as an acute phase protein, its real physiological functions has not been clarified so far." (PMID 24497876, 2014). "We postulate that through this pathway, pK1-5 activates inflammation in hepatoma cells through an induction of TNF-alpha and increases this proinflammatory impact via a TNF-alpha triggered upregulation of VEGF." (PMID 24895598, 2014). "In a study which introduced a mixture of IL-6, IL-1, and TNF-α in murine hepatoma cell line Hepa 1–6, a reduction in PON1 mRNA was observed." (PMID 24799979, 2014). "For example, overexpression of FoxM1 partially protected cancer cells against thiazole antibiotic-mediated cell death and enhanced hepatoma cell resistance to TNF-α–induced apoptosis." (PMID 24148180, 2013). "Here, we reconfirmed the inhibitory effects of AIMs on TNF-induced NF-κB activation which had been reported in hepatocellular carcinoma cells." (PMID 23864892, 2013). "Recombinant CTRP3 reduced glucose output in cultured rat hepatoma cells by suppressing gluconeogenic genes, significantly inhibited LPS-induced IL-6 and TNF-α secretion in THP-1 cells, and reduced NF-κB p65 activity." (PMID 23409033, 2013).